AKT3 (AKT serine/threonine kinase 3)
Diseases named in the same sentence as AKT3 in open-access papers (continued):
Sharing a sentence is not in itself a finding about the gene and the disease.
breast carcinoma (continued). "Akt1 and Akt2 were expressed in all tested breast cancer cell lines, but Akt3 was detectable only in MDA-MB-231 cells." (PMID 21362200, 2011). "Moreover, the knockdown of AKT3 resulted in a moderate reduction in breast cancer cell proliferation." (PMID 40400456, 2025). "Notably, EMT and stemness genes such as ZEB2, SNAIL, TWIST, Gli2, WNT, and AKT3, which are overexpressed in basal-like breast cancer (BLBC), were significantly upregulated in drug-resistant cells." (PMID 38078907, 2023). "However, the most significant effects of Akt3 in terms of growth and proliferation of breast cancer have been shown in TNBC." (PMID 34298660, 2021). "We furthermore identified upregulation of the direct EZH2 target genes CNN3 and AKAP13, that are involved in chemotherapy resistance in colon cancer and breast cancer, respectively, and the genes MYO5A, AKT3 and SPECC1, which are implicated in the evasion of apoptosis." (PMID 33712646, 2021). "Around 11% of human breast cancers show amplification of AKT3." (PMID 33921698, 2021). "However, investigations about the role of AKT3 in breast cancer are scarce and several laboratories reported only minor effects of AKT3 on tumor growth and metastasis." (PMID 33670586, 2021). "Furthermore, the correlation of MRCKα expression with breast cancer formation and progression appears to be at least partly due to the co-amplification with AKT3 and in particular ARID4B." (PMID 33921698, 2021). "Upregulation of HER2 activity in the AKT3 knockdown of 231-BO cells could mimic the bone-metastatic behavior of HER2 positive breast cancer and could explain the increase in bone metastasis." (PMID 33670586, 2021). "Therefore, we aimed to clarify the role of AKT3 in bone metastasis of breast cancer and provide a rationale for an isoform-specific AKT inhibition in breast cancer patients with bone metastases." (PMID 33670586, 2021). "Interestingly, ARID4B, MRCKα and AKT3 are mostly amplified together and show a highly significant co-occurrence of genetic alterations in breast cancer." (PMID 33921698, 2021). "Furthermore, increasing evidence indicates that AKT3 can be an oncogene in many cancers, including osteosarcoma, colorectal cancer, prostate cancer, and breast cancer." (PMID 34882061, 2021). "Knockdown of Akt1 and Akt3 in ErbB2-positive Erα-negative mouse mammary tumor C4 cells caused a substantial decrease in cell proliferation whereas Akt2 knockdown had only a modest effect." (PMID 34298660, 2021). "AKT3 showed an oncogenic effect in the murine MMTV-PymT mammary cancer model." (PMID 33921698, 2021). "However, the knowledge about the role of AKT3 in breast cancer is sparse and should be addressed by further investigations." (PMID 31752925, 2019). "Thus, AKT3 expression is higher in HER2-positive human breast cancer and TNBC than in ER-positive mammary tumors." (PMID 31752925, 2019). "In breast cancer cells, downregulation of AKT3 has also been shown to enhance metastasis." (PMID 31046734, 2019). "However, their study did not include GBM samples, which were reported to have lower linear AKT3 levels compare with those of the other malignancies including breast cancer, ovarian cancer and melanoma." (PMID 31470874, 2019). "Whilst AKT3 is associated with a negative ER-status, findings about the role of AKT3 in regulation of the key properties of breast cancer are sparse." (PMID 31752925, 2019). "In addition, AKT3 was targeted by miR-29 in breast cancer, and cytokine receptor (IL2RB and IL6R) and one component of the PI3K complex (PIK3R3) were also targeted by miR-34a and miR-29, respectively, in DLBCL." (PMID 30820547, 2019). "Only a few studies paid attention to the role of AKT3 in breast cancer." (PMID 31752925, 2019). "According to the TCGA, 28% of breast cancers are AKT3 amplified." (PMID 31752925, 2019).
breast carcinoma (continued). "Of 3 members (AKt1, AKt2, and AKt3) of the AKt family, AKt1 and AKt2 are important signaling molecules related to a diabetic phenotype such as IR; at the genomic level, each is amplified in various cancers including breast cancer." (PMID 29023587, 2017). "Moreover, a recurrent MAGI3-Akt3 fusion protein that results in a truncated form of the MAGI3 gene fused in frame to AKT3 at the E17 residue of Akt3 has been identified in breast cancers." (PMID 27004402, 2016). "Three Akt isoforms are expressed in breast cancer cells (e.g. Akt1, Akt2,and Akt3)." (PMID 23874830, 2013). "Akt2 and Akt3, are genomically amplified in several ovarian, pancreatic and breast cancers." (PMID 22511990, 2012). "We have analysed an additional 547 primary breast cancers without detecting AKT2 or AKT3 E17K mutations." (PMID 18813315, 2008). "Akt3 expression is exclusive to more advance and hormone-independent breast cancer cells." (PMID 18184439, 2008). "Using a two-site chemiluminescence-linked immunosorbent assay, we measured the quantitative expression levels of total phosphorylated (P-S473) Akt (Akt1/Akt2/Akt3) on cytosol fractions obtained from fresh frozen tissue samples of 156 primary breast cancer patients." (PMID 15987444, 2005). "In this study, we sought to compare the concordance of pathogenic alterations in PIK3CA, AKT1, AKT2, AKT3, and PTEN detected by tissue-based FoundationOne®CDx and blood-based FoundationOne®Liquid CDx in contemporaneous samples collected from patients with breast cancer." (PMID 40597213, 2025). "In cells grown in 3D, progestins regulate a group of breast cancer-associated genes that are also regulated in 2D including CDH10, PGR, CHEK2, LSP1, TERT, SDPR, but also a new set of 3D-exclusive genes, associated to the ECM including members of the integrin family, Laminins, and AKT3." (PMID 38565950, 2024). "In addition, AKT3 mediates resistance to tamoxifen in HER2-positive breast cancer cells." (PMID 31752925, 2019). "Additionally, we expanded our binding analysis to full-length Akt2 and Akt3 to investigate whether the other Akt isoforms interact in a comparable manner with DNA-PKcs in NSCLC as well as in breast cancer cells." (PMID 29090098, 2017). "Indeed, AKT3 is usually involved in prostate and breast cancer." (PMID 27378931, 2016). "Our data are consistent with reports that Akt3 may be involved in breast cancer invasion." (PMID 25575302, 2015). "Our study is one of the largest analytical studies of pathogenic alterations in PI3K/AKT pathway genes (PIK3CA, AKT1, AKT2, AKT3, and PTEN) among patients with breast cancer." (PMID 40597213, 2025). "For instance, our previous investigation suggested LINC00960 to promote breast cancer via the hsa-miR-34a-5p, hsa-miR-16-5p, BMI1, KRAS, and AKT3 network." (PMID 39995981, 2025). "Numerous studies have elucidated the role of AKT3 as a driver of endocrine therapy and AKT inhibitor resistance in ErbB2-driven breast cancer and breast cancer in general." (PMID 39614261, 2024). "Our study found upregulation of AKT1 and AKT3, which are involved in the signaling pathway of PI3K, and previous studies have demonstrated overactivation of the PI3K pathway in breast cancer." (PMID 38225865, 2024). "Our results showed that the genes AKT3, GFAP, ADCYAP1R1, VDAC1, and C4A have significant transcriptomic alterations in FTD along with the comorbidity status with COVID-19 and breast cancer." (PMID 37834358, 2023).
breast carcinoma (continued). "Results showed that the gene VDAC1 is highly expressed in all the subtypes, whereas AKT3 is expressed in TNA, TNB, and H-subtypes, indicating that these genes have a significant role in Breast cancer at the single-cell level." (PMID 37834358, 2023). "To model acquired resistance in breast cancer, we previously generated MK2206-resistant lines, and showed a prominent role of Akt3 in mediating resistance." (PMID 36291790, 2022). "A cBioPortal analysis shows ≈50% of breast cancers with genomic aberrations in PIK3CA, AKT1, AKT2, AKT3, and/or ESR1,suggesting relevance of this signaling axis in breast cancer." (PMID 33498407, 2021). "AKT3 amplification or translocation with MAGI3 gene, leading to constitutive AKT3 activity is reported in breast cancer." (PMID 33498407, 2021). "Several studies have also found a role for Akt3 in tumor suppression; knockdown of Akt3 promotes metastasis in vivo by activating HER2 and DDR kinases in bone-seeking breast cancer cells." (PMID 34591413, 2021). "Upregulation of AKT3 has been suggested as a potential mechanism of resistance to allosteric AKT inhibitor MK2206, using preclinical breast cancer models." (PMID 34853384, 2021). "In a similar way, interaction of CFIm25 with distal region of AKT3 3′-UTR mRNA, facilitates down-regulation of AKT3, which then regulates migration and metastasis in breast cancer cells." (PMID 32665581, 2020). "These two examples can clarify how CFIm25 interaction with distal region of EGFR and AKT3 3′-UTR mRNAs, can facilitates suppression of breast cancer tumorigenicity and metastasis, respectively." (PMID 32665581, 2020). "Many candidate genes emerged to be related to this breast cancer subtype, such as AKT1, AKT3, INPP4B, and EGFR." (PMID 30630526, 2019). "Increased AKT3 expression not only promoted prostate cancer proliferation, but also conferred resistance to AKT inhibitor in breast cancer and PLK inhibitors in human colorectal cancer." (PMID 28316978, 2017). "AKT3 is an oncogene of known relevance in breast cancer, and as a proof of principle we show that inhibition of phosphoinositide 3-kinase (PI3K) activity, a protein upstream of AKT3, suppressed proliferation in TNBC preneoplastic cells." (PMID 28160548, 2017). "AKT1 localizes to the cytoplasm in a number of human breast cancer cell lines, whereas AKT2 is present in mitochondria and the cytoplasm and AKT3 exhibits a nuclear and nuclear membrane distribution." (PMID 28082369, 2017). "This reflects the frequent activation of receptor tyrosine kinases, activating mutations in PI3KCA and AKT1, as well as overexpression of AKT2 or AKT3 and inactivation of the tumor suppressor gene PTEN in breast cancer." (PMID 26741489, 2016). "The mutational and mRNA expression status of PIK3CA, PIK3R1 and AKT1, and expression status of other genes involved in the PI3K pathway (EGFR, PDK1, PTEN, AKT2, AKT3, GOLPH3, WEE1, P70S6K) were assessed in a series of 458 breast cancer samples." (PMID 24229379, 2013). "Akt isoform specificity has yet to be extensively studied in breast cancer in relation to FASN, although prostate cancer studies have revealed a relationship between Akt3 and FASN involving the two as downstream effectors of peroxisome proliferator-activated receptor gamma (PPARG) activation." (PMID 34298660, 2021). "Further genomic analysis of human breast cancers revealed that MRCKα is frequently co-amplified with the oncogenes ARID4B and AKT3 which might contribute to the prognostic value of MRCKα expression." (PMID 33921698, 2021). "We demonstrated that AKT3 plays a crucial role in bone-seeking breast cancer cells by promoting metastatic potential without facilitating tumor-induced osteolysis." (PMID 33670586, 2021). "Taken together, our data suggest that an AKT3 knockdown in the bone-seeking breast cancer cell line 231-BO increases metastasis to bone but does not facilitate the vicious cycle of osteolysis." (PMID 33670586, 2021).
breast carcinoma (continued). "In vitro, downregulation of AKT2, but not AKT1 or AKT3, attenuated cell proliferation and 3D spheroid growth in PTEN-deficient prostate and breast cancer cells." (PMID 33276499, 2020). "Therefore, exclusive interaction of CFIm25/CPSF1 complex with distal region of EGFR and AKT3 3′-UTR coding mRNA, would guarantee suppression of breast cancer progression." (PMID 32665581, 2020). "But another study observed that AKT3 expression at the RNA level is not exclusively for human breast cancer probes and can also be found in normal breast tissue." (PMID 31752925, 2019). "Another study points out the importance of AKT3 in TNBC by reporting amplification of AKT3 in 14% of TNBC versus 3% of luminal breast cancer and upregulation of mRNA in 21% of TNBC versus 2% of luminal human breast cancer according to a TCGA analysis." (PMID 31752925, 2019). "In opposition to breast cancer cells, ovarian cancer cells as well as non-transformed ovarian cells display a higher expression and activation of AKT3 compared to the other isoforms, suggesting AKT3 is more important in ovarian cancer than in breast cancer." (PMID 31752925, 2019). "Protein abundance and activity of Akt3 have previously been suggested to contribute to the more aggressive clinical phenotype of androgen non-responsive prostate and breast cancers." (PMID 22347457, 2012). "Another study in 402 ERα-positive breast cancer patients showed clearly that cytoplasmic Akt1 and Akt3, but not Akt2, expression was correlated significantly with pAkt expression." (PMID 18184439, 2008). "However, in CRPC, the increased Akt3 levels are not reversible, whereas in our breast cancer model, upregulation of Akt3 involved an epigenetic mechanism." (PMID 36291790, 2022). "Since TGFβ-stimulation was shown to increase CTGF expression in breast cancer cells, we propose that this is regulated at least in part via the PI3K/AKT3 pathway in an isoform-specific manner, because the diminished increase in CTGF expression could only be observed after AKT3 knockdown." (PMID 33670586, 2021). "Based on next-generation sequencing analysis, genetic alteration in Akt1 (E17K and other pathologic mutations) was significantly enriched in metastatic breast cancer compared to primary breast cancer and Akt1, but not Akt2 or Akt3, was identified as an actionable target." (PMID 34298660, 2021). "Although, AKT1, AKT2 and AKT3 share a high homology, are activated and regulated by the same upstream mechanisms and share a wide range of substrates, the three isoforms exert non-redundant and partly opposing roles in breast cancer." (PMID 31752925, 2019). "The levels of Akt3 could be detected at very low but similar levels in the mammary tumors from three different genotypes (data not shown)." (PMID 23919516, 2013). "Evaluation of Akt1, Akt2 and Akt3 revealed that Akt1 and Akt2 can be detected in both WT mammary tissue and mammary tumors while Akt3 could not be detected in either WT mammary tissue or mammary tumors." (PMID 23919516, 2013). "Inhibition of AKT3 in an early stage of breast cancer without metastases or at the beginning of the metastatic cascade seems not expedient, whereas in patients with already developed bone metastases, inhibition of AKT3 could be advantageous." (PMID 33670586, 2021). "On the contrary, the levels of AKT3 mRNA, protein, and enzymatic activity are significantly increased in estrogen receptor negative (ER−) and triple negative (ER−, Progesterone Receptor negative, Her2/neu negative; ER−PR−Her2/neu−) breast cancers, promoting cell proliferation and tumor growth." (PMID 27323778, 2016). "Whereas AKT2 does not display such a phenotype, AKT3 promotes angiogenesis via VEGF and c-Myc in breast cancer." (PMID 31752925, 2019). "This has been complemented by data indicating a higher AKT3 expression and activation in HER2-positive breast cancer, but not in ER-positive cells." (PMID 31752925, 2019).
breast carcinoma (continued). "Investigations of ER positive human breast cancer probes revealed AKT1 deletions in 4.8%, AKT1 amplifications in 1%, AKT2 deletions in 21.1%, interestingly no AKT2 amplifications, no deletions of AKT3, but AKT3 amplifications in 9.9% of investigated ER-positive human breast cancers." (PMID 31752925, 2019). "However, there is growing evidence that the different isoforms AKT1, AKT2 and AKT3 have non-redundant and partly opposing effects in tumorigenesis, making pan-AKT inhibition in breast cancer inappropriate." (PMID 31752925, 2019).
melanoma (80 papers, 2008 to 2025). A malignant, usually aggressive tumor composed of atypical, neoplastic melanocytes. "Selective activation of the AKT3 subtype combined with PTEN loss has been observed in 43%–60% of sporadic melanomas, indicating elevated levels of active AKT3 in the late stages of the disease." (PMID 40041495, 2025). "Studies using RNA interference targeting AKT3 or PTEN mutations reduced the tumorigenic potential of melanoma cells." (PMID 39594467, 2024). "The hyperactivation of the pathway is present in more than 50% of melanomas as a result of AKT3 amplification and the subsequent loss of the tumour suppressor PTEN through epigenetic silencing or deletion." (PMID 39594467, 2024). "It has been observed that PI3K activity is increased in melanoma due to loss of PTEN or increased levels of Akt3 activity, and that plays a crucial role in early melanoma development." (PMID 33172190, 2020). "Due to the fact that PTEN is known to inhibit AKT activity (predominantly AKT3 in melanoma) and thus promotes melanoma cell apoptosis, loss of PTEN is a crucial event during melanoma development and progression." (PMID 31378787, 2019). "Particularly, AKT3 is abundantly expressed in the nervous system and has been associated with the development of neural crest-derived tumors such as melanoma or involved the progression of gliomas through activation of the DNA repair pathway." (PMID 26824183, 2016). "Activation of AKT3 in response to BRAF inhibitor PLX4720 or BRAF siRNA was implicated in the resistance of primary three-dimensional cultures of melanoma cells to BRAFV600E inhibitors." (PMID 24743024, 2014). "Approximately 70% of melanomas have elevated Akt3 signaling both for increased gene copy number and PTEN loss." (PMID 22623890, 2012). "We also identified the analogous E17K mutation in AKT3 in two different tumours (from the same patient) and in two human melanoma cell lines." (PMID 18813315, 2008). "This represents the first report of AKT mutations in melanoma, and the initial identification of an AKT3 mutation in any human cancer lineage." (PMID 18813315, 2008). "Remarkably, a previously unidentified AKT3 E17K mutation was detected in two melanomas (from one patient) as well as two cell lines." (PMID 18813315, 2008). "When we further investigated the possible upregulation of other Akt kinases that could be linked to the proliferation of cancers, including melanoma, we found Akt3 to be upregulated in TRCs by more than two-fold." (PMID 32962144, 2020). "An E17K mutation in AKT3 was also identified in one case of primary human melanoma, which may have similar functional consequences to AKT1, although this has not been functionally verified." (PMID 28082369, 2017). "Mutations of AKT3 at both E17K and other sites were reported in melanoma and endometrial carcinoma." (PMID 22666248, 2012). "Mutation of AKT3 has been detected in some melanoma samples." (PMID 23006971, 2012). "A recent report documents the mutation of AKT3 in some melanoma samples." (PMID 21422497, 2011). "Rare activation mutations in the AKT1 or AKT3 isoforms have been found in sun-exposed melanoma subtypes, and AKT overexpression may be associated with melanoma growth in situ." (PMID 19949544, 2009). "The AKT3 E17K mutation results in activation of AKT when expressed in human melanoma cells." (PMID 18813315, 2008). "The discovery of an AKT3 mutation in melanoma is consistent with previous data that suggest that this isoform of AKT may be particularly critical in this cancer." (PMID 18813315, 2008). "PLEKHA5-L upregulates oncogenes (e.g., HRAS, AKT3) to enhance melanoma migration and proliferation, while concomitantly elevating the expression of therapy-resistance mediators PD-L1 and ABC transporters." (PMID 40356756, 2025).